Y_RNA (Y RNA )
Gene: Miscellaneous RNA gene on chromosome 17 (82,417,226 to 82,417,321, forward strand). Ensembl gene ENSG00000201239.
Homologues: Orthologues: chimpanzee Y_RNA (98% identical), macaque Y_RNA (89% identical). Paralogues in human: RNY4 (86% identical), RNY4P3 (85% identical), RNY4P6 (85% identical), Y_RNA (84% identical), RNY4P14 (83% identical), RNY4P24 (82% identical), Y_RNA (82% identical), RNY4P19 (81% identical), RNY4P7 (81% identical), RNY4P9 (81% identical), RNY4P10 (80% identical), RNY4P13 (80% identical), and 88 more.